STAT3 (signal transducer and activator of transcription 3)
Diseases named in the same sentence as STAT3 in open-access papers (continued):
Sharing a sentence is not in itself a finding about the gene and the disease.
colitis (continued). "Both IL-22 and IL-6 activate STAT3 signaling, but epithelial STAT3 activation in DSS-induced colitis depends more on IL-22 than on IL-6." (PMID 36142515, 2022). "To establish the impact of STAT3 GOF on Treg function in vivo, we again utilized the T cell transfer model of colitis, as the role of Tregs in treating and preventing disease in this model has been well established." (PMID 36136607, 2022). "In colitis models, inhibition of RhoA/ROCK activity significantly protects the intestinal epithelial barrier dysfunction and colonic inflammation via STAT3 and NF-κB signaling pathways." (PMID 36286060, 2022). "Notably, STAT3 phosphorylation in immune cells may exert different inflammation effects in colitis." (PMID 36590229, 2022). "In summary, our investigations revealed a critical role of STAT3 activation in COL1+ CAFs, suggesting that targeting of STAT3 in type I collagen-expressing fibroblasts could represent a promising therapeutic strategy in colitis-associated CRC and possibly other tumor entities." (PMID 35326623, 2022). "In contrast, Indigo Naturalis can inhibit STAT1/STAT3 signaling and protect against DSS-induced colitis in mice." (PMID 35873579, 2022). "It is known that STAT3-NF-κB and RhoA/ROCK signaling pathway is closely correlated with epithelial barrier dysfunction and conical inflammation in the colitis model." (PMID 36286060, 2022). "Another study reported that curcumin can ameliorate trinitrobenzene sulfonic acid (TNBS)-induced severe colitis by downregulating the phosphorylation of JAK2, STAT3, and STAT6 in colonic tissues." (PMID 34068714, 2021). "The colon tissue from SMILE overexpressing DSS-induced colitis mice exhibited higher levels of SMILE and AMPK and lower levels of mTOR and STAT3 than that of mock vector-treated mice." (PMID 34211461, 2021). "Mechanistically, LEP treatment was found to block the activation of PPARγ/NF-κB and STAT3 pathways by upregulating PPARγ expression and retarding the phosphorylation of NF-κB p65, IκB, and STAT3 in DSS-induced colitis." (PMID 33981232, 2021). "EBFT induces colitis and tumorigenesis via IL17 induction, activation of STAT3 and recruitment of polymorphonuclear immature myeloid cells on lamina propria." (PMID 33841394, 2021). "It was reported that curcumin and semibionic extraction of compound turmeric can inhibit the proinflammatory signaling by STAT3 and TNF-α in experimental colitis." (PMID 34221084, 2021). "A similar correlation between miR-124 and STAT3 expression levels was observed in DSS and IL-10 KO mouse models of colitis." (PMID 34571853, 2021). "In mice, activation of STAT3 and expression of SOCS3 is characteristic for the development of IBD and colitis, with SOCS3 acting as a regulatory mechanism to limit pathogenesis, which is primarily driven through macrophages." (PMID 34604264, 2021). "In DSS-induced colitis mice, baicalein decreased the levels of inflammatory mediators and significantly downregulated the expression of SphK1, S1PR1, and p-STAT3 in the colon." (PMID 33995078, 2021). "Taken together, STAT3 promotes pro-inflammatory signals in acquired immune cells in IBD, whereas its role in innate immune cells is the suppression of colitis by enhancing mucosal protection." (PMID 34068714, 2021). "Compared with the sham group, the levels of p-JAK2, p-STAT3, and SOCS3 significantly increased in the colitis group." (PMID 34594215, 2021). "In particular, the expression of miR-124 was found inversely correlate with STAT3 in both DSS-induced and IL-10 knockout colitis mice models and CRC patients, as well." (PMID 33921348, 2021). "Pretreatment with TAK-242 significantly reduced JAK2/STAT3 protein expression and promoted the phosphorylation of JAK2/STAT3, exerting protective effects on colitis." (PMID 32762699, 2020).
colitis (continued). "This extract was found to inhibit inducible NF-κB and STAT3 activation and the subsequent inductions of pro-inflammatory mediators, and to protect mice from DSS-induced colitis, which is a well-established experimental model for IBD." (PMID 32059355, 2020). "On the other hand, compared with that observed inwith the control group, the DSS-induced colitis model group had greatly increased mRNA levels of TLR4, JAK2 and STAT3." (PMID 32762699, 2020). "At the initiation of colitis, colonic epithelium-specific mammalian target of rapamycin complex 1 induces COX-2 via p-STAT3, which then mediates the Th-17 response." (PMID 33092149, 2020). "JAK2 and STAT3 were upregulated in DSS-induced colitis tissue, while phosphorylated JAK2 and STAT3 were significantly downregulated." (PMID 32762699, 2020). "We have identified distinct roles of IL-17A and IL-17F in modulating DSS-induced colitis in mice and we demonstrated the benefit of quercetin in colitis dependent on Arg-1 secreted by MDSC after ESR/STAT3 activation." (PMID 32391010, 2020). "IL-6 binds to soluble or membrane-bound IL-6 receptors and triggers the activation of STAT3; STAT3 is highly phosphorylated in DSS-induced colitis in mice and human IBD patients." (PMID 32859970, 2020). "LIF protects colitis through regulating the function of lamina propria lymphocytes via the STAT4 signaling and repair function of IECs via the STAT3/YAP signaling." (PMID 32719388, 2020). "Collectively, this study demonstrates that IFN-γ treatment promoted exosomes from MSCs to attenuate colitis through increasing the level of miR-125a and miR-125b, which binding on 3′-UTR of Stat3 to repress Th17 cell differentiation." (PMID 32733020, 2020). "Quercetin treatment activated ESR signal in MDSC and in turn boosted STAT3 phosphorylation, dramatically increased MDSC percentage and up-regulated Arg-1 and iNOS in MDSC during colitis." (PMID 32391010, 2020). "IL-21 also promotes IL-22 expression in mucosal T-cells through a mechanism involving STAT3, retinoid-related orphan receptor γt, and aryl hydrocarbon receptor, thereby helping protect immunodeficient mice from DSS colitis." (PMID 32855621, 2020). "In the present study, we found the phosphorylation of STAT3 was significantly increased in both colon tissues of DSS-induced colitis mice and LPS challenged macrophage RAW246.7 cells, indicating that STAT3 was activated under inflammatory microenvironment." (PMID 32411289, 2020). "Treatment with different doses of TAK-242 in DSS-induced colitis mice significantly enhanced the expression of phosphorylated JAK2 and STAT3." (PMID 32762699, 2020). "GA attenuates experimental colitis by suppressing IL-6, IL-1β, TNF-α, IL-17 and IFN-γ production and inhibiting p65-NF-κB and IL-6/p-STAT3 (Y705) activation." (PMID 31026283, 2019). "Another regulator of STAT3 activation in Th17 is the tyrosine phosphatase SHP1, which dampens IL-6- and IL-21-driven Th17 development and limits colitis in mice." (PMID 31480382, 2019). "CST treatment led to an increase of colonic p-STAT3 level and Stat3 mRNA levels in DSS-induced colitis when compared with the DSS control group." (PMID 30241336, 2018). "Consistent with previous reports, we observed that TNBS-induced colitis invariably promoted inflammation in the colon with elevated levels of IL-1β, IL-6, TNF-α and an increased expression of JAK2, STAT3, and p-STAT3." (PMID 30042683, 2018). "Compared with the normal group, mRNA levels of TLR4, NF-κB, IL-6, STAT3, and JAK2 in colitis rats remarkably increased (P < 0.001, P < 0.01)." (PMID 30042683, 2018). "The results provided further evidences of the effects of CP on suppression of colitis and indicated the key role of IL-6/JAK2/STAT3 pathway as relevant targets of CP." (PMID 30042683, 2018). "As a mediator of IL-6-induced STAT3 activation, TRIM27 plays important roles in DSS-induced colitis and AOM/DSS-induced CAC development." (PMID 30143645, 2018).
colitis (continued). "We conclude that TRYP improves the health condition of mice with DSS induced colitis by regulating the TNF-α/NF-κBp65 and IL-6/STAT3 signaling pathways via inhibiting the degradation of IκBα and the phosphorylation of STAT3." (PMID 29724065, 2018). "An attenuated trend of the expression of p65, pp65, TLR4, STAT3, p-STAT3, JAK2 in TNBS-induced colitis rats was observed in the groups treated with CP." (PMID 30042683, 2018). "Here, we identified, for the first time, a potential novel mechanism by which CST ameliorates the severity and onset of colitis through regulation of TJ dynamics and intestinal epithelial cells (IEC) homeostasis via a STAT3-dependent pathway." (PMID 30241336, 2018). "STAT3 was also reported to be excessively phosphorylated in epithelial and lamina propria cells of IBD patients and in DSS-induced colitis mouse models." (PMID 30498394, 2018). "STAT3 is critical in driving disease in T-cell transfer models of colitis, the authors propose that the DUSP2−/− phenotype is due to elevated STAT3 activity." (PMID 30429852, 2018). "It is also known that expression of the novel adipokine CTRP4 suppresses colitis in mice with a marked downregulation of ERK, AKT and STAT3." (PMID 28300788, 2017). "IL-6−/− mice exhibited a more severe DSS-induced colitis, elevated apoptosis, and decreased IEC proliferation, similar to mice with IEC-specific deletion of STAT3." (PMID 28852270, 2017). "Our results suggest that Grim19 inhibits proinflammatory cytokine and p-STAT3 expression to suppress inflammation, which suggests a novel therapeutic strategy for DSS induced colitis." (PMID 27258062, 2016). "Grim19 production was increased significantly, whereas STAT3 expression was decreased significantly, in DSS induced colitis mice treated with Grim19 compared with control mice." (PMID 27258062, 2016). "The transcriptional activity of STAT3 has been suggested to induce TNF-α production and plays a role in the pathogenesis of DSS induced colitis." (PMID 27258062, 2016). "Grim19 expression was increased significantly, whereas STAT3 production was reduced significantly, in DSS induced colitis mice treated with Grim19 compared with control mice." (PMID 27258062, 2016). "The effect of STAT3 in intestinal inflammation is supported by the fact that activated STAT3 has been found in human IBD and animal colitis models." (PMID 26075036, 2015). "Our data also demonstrate that specific cytokines, as well as STAT3 activation, require SK1/S1P from both hematopoietic and extra-hematopoietic sources in acute DSS-induced colitis." (PMID 25460165, 2014). "The expression levels of S100A9 mRNA were notably suppressed in the group of mice treated with si-STAT3/CH-NPs, resulting that STAT3 regulated the expression level of S100A9 in the CECs in DSS-induced colitis." (PMID 22962574, 2012). "More recently, we have found that treatment with Vidofludimus attenuated the activation of STAT3 and NF-κB pathways, as well as IL-17 production, in murine splenocytes and TNBS-induced colitis." (PMID 22506136, 2012). "We generated a mouse model of experimental colitis induced by dextran sulfate sodium (DSS) and showed that IL-6 triggered S100A9 production in CECs, which was mediated through STAT3 activation." (PMID 22962574, 2012). "IL-6 and S100A9 expression, signal transducer and activator of transcription 3 (STAT3) phosphorylation, and infiltration of immune cells were analyzed in mice with dextran sulfate sodium (DSS)-induced colitis." (PMID 22962574, 2012). "In genetic complementation studies, we found functional redundancy between the IL6 and IL11 signaling in intestinal epithelium, where both cytokines were equally potent in conferring Stat3-dependent, epithelial resistance to DSS-induced apoptosis and colitis." (PMID 20478049, 2010).
colitis (continued). "In our study, we also found that the IEC-specific deletion of STAT3 (Villin-Cre STAT3fl/fl) reduced the secretion of anti-inflammatory cytokines IL-10 and IL-22 and augmented epithelial erosions and mucosal barrier disruption after DSS-induced colitis." (PMID 39773987, 2025). "In addition, hesperetin significantly inhibited the phosphorylation of JAK2 and STAT3 and promoted the expression aof SOCS3, thereby alleviating colitis." (PMID 40078988, 2025). "In addition, STAT3 and ERK pathways in intestinal epithelium were impaired during experimental colitis, and iron content significantly interrupted the expression of p-STAT3 and p-ERK1/2 within small intestine." (PMID 40416374, 2025). "Several experimental studies have investigated the therapeutic potential of PTX in models of colitis; however, the present study is the first to elucidate its modulatory effects on the SPHK1/S1P, IL‐6/STAT3, AMPK/mTOR/NLRP3, and ZO‐1 signaling pathways in experimental colitis." (PMID 40387460, 2025). "In this study, we aimed to investigate the anti-colitis efficacy of CSCC and explore whether and how Gpr43 inhibits the STAT3/NLRP3 signaling pathway, thereby mediating the protective effects of CSCC on the intestinal barrier." (PMID 39329121, 2024). "Similarly, this compound inhibits Th17 and Th1 cell differentiation by reducing STAT3 and STAT4 phosphorylation, respectively, and suppresses mTORC1 pathway activity independently of PI3K/AKT and ERK signaling in DSS-induced colitis mice." (PMID 39494333, 2024). "However, the KO of HTR2B in the intestinal epithelial cells of mice aggravates the severity of AOM/DSS-induced colitis by inhibiting TGF-β/SMAD signaling and activating IL-6/STAT3 signaling." (PMID 39180723, 2024). "At the same time, STAT3 knockout also reduced the differences in the expression of IL-6, TNF-α, and IL-1β, as well as ZO-1, occludin, BCL-2, and BAX in the colons of mice with colitis induced by different diets." (PMID 38233383, 2024). "Therefore, we investigated the STAT3 signaling pathway and assessed the activity of the STAT3 pathway in mice with DSS-induced colitis." (PMID 39329121, 2024). "Taken together these studies reveal intriguing observations wherein the absence of Rela and Stat3 in hepatocytes protects mice from DSS-induced colitis." (PMID 39137024, 2024). "Given the phosphorylation inhibition function of SOCS1, we speculated that UTI regulates the JAK2/STAT3/SOCS1 axis to reduce an inflammatory response and barrier impairment in colitis." (PMID 38397811, 2024). "This further strengthens the hypothesis that in the context of colitis, MALT1 might promote the activation of STAT3." (PMID 37108564, 2023). "Remarkably, while C188-9 treatment significantly alleviated the severity of colitis in the eEF2K KO group, this STAT3 inhibitor did not affect the severity of the disease in the WT group, as determined by body weight, colon size, and pathologic score." (PMID 37875468, 2023). "The increase in STAT3 expression in eEF2K knockout CD4+ T cells prompted us to explore the role of this transcription factor in the eEF2K-mediated regulation of colitis." (PMID 37875468, 2023). "For example, disruption of signal transducer and activator of transcription 3 (Stat3) S-palmitoylation cycling by genetic deletion of Zdhhc7 or pharmacological inhibition of APT-2 ameliorates inflammatory gene expression and colitis in an animal model of inflammatory bowel disease." (PMID 37926281, 2023). "Considering that the synthesis of PGE2 is mediated by COX-2 and the phosphorylation of STAT3 can upregulate COX-2 expression, it is plausible to speculate that STAT3 serves as a pivotal protein in mediating the activity of POLP in colitis." (PMID 37375369, 2023). "The NF-κB/IL-6/Stat3 and JAK2/Stat3 pathways may be critically involved in CAC tumorigenesis, and it was found that AFE ameliorated colitis and inhibited CAC by downregulating these two inflammation-related signaling pathways." (PMID 38004214, 2023).
colitis (continued). "In patients with IBD, STAT3 is activated by IL-6 as well as other cytokines and factors in the microenvironment; IL-11, IL-22, HGF, and EGF family members are active during the colitis stage, and may also be active during CAC/CRC tumorigenesis." (PMID 38002302, 2023). "The STAT3 and mTOR pathways have also been demonstrated to promote Th1 cells producing IL-10 by using butyrate to deal with the T cells from IBD patients and the DSS model, therefore limiting colitis." (PMID 37371485, 2023). "This outcome is not verified in vivo and does not confirm the impact of hyperactivated STAT3 on ferroptosis in colitis." (PMID 37153794, 2023). "In TNBS-induced colitis, Berberine increases the expression of sIgA in the colon by downregulating STAT1 and STAT3 phosphorylation, inhibiting the NF-κB signaling pathway, decreasing Th1/Th17, and reducing pro-inflammatory cytokines, which can regulate the immune response homeostasis." (PMID 35873579, 2022). "In addition to STAT6, the shown M2 phenotype can also be promoted through the activation of STAT3, as supported by our results of increased STAT3 phosphorylation in CD26−/− mice during colitis development." (PMID 35628317, 2022). "In our data, BA treatment decreased the NF-κB and STAT3 activities and the expression of COX2 and iNOS in the DSS-treated mice model, which provides evidence of how BA has an anti-inflammatory effect in DSS-induced colitis." (PMID 36286060, 2022). "F nucleatum also promotes the secretion of proinflammatory cytokines (TNF‐α, IFN‐γ, IL‐1β, IL‐6, and IL‐17) and activates the signal transducer and activator of transcription 3 (STAT3) signaling pathway, thereby inducing the expansion of Th1 and Th17 cells in the DSS‐induced colitis model." (PMID 35244953, 2022). "Of particular interest, our results found that pea albumin significantly alleviated the upregulation of phosphorylation of NF-κB and STAT3, indicating that pea albumin contains bioactive compounds with the ability to block the NF-κB and STAT3 signaling pathways in DSS-induced colitis." (PMID 36079868, 2022). "The results indicate that STAT3 phosphorylation and nuclear translocation was attenuated by treatment with the P2RY13 antagonist MRS2211 in inflammatory stimulated NCM460 cell and DSS induced colitis." (PMID 35982893, 2022). "Targeting oncomiRs such as miR-21 and miR-181-b, and lack of PDCD4 in colitis and CAC mice models have been associated with enhanced IL-6 production, intensified activity of STAT3 signaling pathway, enhanced colitis and proliferation of tumor cells." (PMID 35410210, 2022). "An important finding in our study was the decreased phosphorylation of JAK2/STAT3 after NBD combined with FMT treatment, thus suggesting that inhibition of the JAK/STAT pathway might be involved in the anti-colitis effect of combination therapy." (PMID 36424592, 2022). "This is best exemplified by enterotoxigenic B. fragilis-induced colitis and tumorigenesis in ApcMin/+ mice, which both require activation of T helper type 17 (TH17) cells via signal transducer and activator of transcription-3 (Stat3)." (PMID 33969420, 2021). "Moreover, gastric administration of arbutin considerably reversed the expression changes of p-JAK2, p-STAT3, and SOCS3 in colitis." (PMID 34594215, 2021). "Similarly, assessments on polysaccharides extracted from Aloe vera on UC-animal models depicted an improvement in colitis, via JAK2, p-JAK2, STAT-3, and p-STAT3 protein expression." (PMID 34912469, 2021). "Furthermore, both MSCs and EVs have an equivalent ability to inhibit inflammation in the DSS colitis model by inhibiting JAK, JNK 1/2, and STAT3 signaling." (PMID 33256827, 2020). "TAK-242 markedly alleviated DSS-induced colitis symptoms and colonic lesions by promoting IL-10 release, inhibiting IL-17 release, downregulating TLR4 and JAK2/STAT3 mRNA and protein expression and increasing JAK2/STAT3 phosphorylation." (PMID 32762699, 2020).